ZFAS1 (ZNFX1 antisense RNA 1)
Diseases named in the same sentence as ZFAS1 in open-access papers (continued):
Sharing a sentence is not in itself a finding about the gene and the disease.
hepatocellular carcinoma (51 papers, 2016 to 2026). A malignant tumor that arises from hepatocytes. "Nevertheless, the intricate biological significance and underlying mechanism of ZFAS1 in the initiation and progression of hepatocellular carcinoma (HCC) remain largely unexplored." (PMID 39001904, 2024). "ZFAS1 is associated with the malignant status and prognosis of patients with hepatocellular carcinoma, and the ZFAS1/miR-150-5p axis is involved in hepatocellular carcinoma progression." (PMID 36855431, 2023). "Moreover, ZFAS1 has also been associated with drug resistance in multiple cancer types, such as melanoma, ovarian cancer, and hepatocellular carcinoma." (PMID 40697388, 2025). "Although previous studies have implicated ZFAS1 in mediating apoptosis in myocardial infarction models and promoting metastasis in hepatocellular carcinoma, its functional role during viral encephalitis remains unclear." (PMID 41214723, 2025). "In our study we profiled expression of disease-associated lncRNAs in CRC tumor tissues and identified ZFAS1 (zinc finger antisense 1), previously observed to be tumor suppressor gene in human breast cancer and oncogene in hepatocellular carcinoma, to be up-regulated in CRC tissue." (PMID 26506418, 2016). "Analysis of 11 lncRNAs across seven cancer types has revealed that ZFAS1 was notably overexpressed in hepatocellular carcinoma (HCC)." (PMID 39333489, 2024). "The results of the CCK-8 assay showed that overexpression of ZFAS1 promoted the proliferation of HepG2 cells, while silencing ZFAS1 inhibited the proliferation of hepatocellular carcinoma cells." (PMID 36855431, 2023). "We demonstrate that ZFAS1 is increased in hepatocellular carcinoma tissues and correlated with the malignant status and prognosis of hepatocellular carcinoma patients." (PMID 36855431, 2023). "Together, these findings implied that ZFAS1 promoted the progression of hepatocellular carcinoma cells by regulating miR-150-5p." (PMID 36855431, 2023). "The results showed that the expression of ZFAS1 was closely related to the occurrence and development of hepatocellular carcinoma." (PMID 36855431, 2023). "The results demonstrated that three lncRNAs (ZFAS1, FBXL19-AS1 and AC068473.5) were associated with the prognosis of patients with hepatocellular carcinoma." (PMID 36855431, 2023). "We evaluated the relationship between the expression of ZFAS1 and various clinicopathological parameters in patients with hepatocellular carcinoma." (PMID 36855431, 2023). "In hepatocellular carcinoma, lncRNA ZFAS1 potentiates the development of hepatocellular carcinoma via the miR-624/MDK/ERK/JNK/P38 signaling pathway." (PMID 36855431, 2023). "In hepatocellular carcinoma, ZFAS1 has been identified as a tumor suppressor gene that can affect the progression of hepatocellular carcinoma through various regulatory pathways." (PMID 36855431, 2023). "Dysregulation of ZFAS1 has been found in hepatocellular carcinoma, gastric, colorectal, breast cancer and acute myocardial infarction patients." (PMID 35112985, 2022). "In endometrial cancer stem cells, linc-RoR bound miR-145 in a similar manner, and ZFAS1 bound miR-150 in hepatocellular carcinoma." (PMID 33422052, 2021). "Consistently, upregulation of lncRNA ZFAS1 has been found in acute promyelocytic leukemia and hepatocellular carcinoma." (PMID 32515146, 2020). "ZFAS1 was previously observed to be tumor oncogene in hepatocellular carcinoma and esophageal squamous cell carcinoma." (PMID 33391210, 2020). "But in hepatocellular carcinoma ZFAS1 serves as an oncogene and promotes cancer metastasis by regulating the expression of related genes such as MMP14 and MMP16." (PMID 32760219, 2020). "Dysregulation of ZFAS1 has been reported in hepatocellular carcinoma, breast cancer and many other types of human cancers." (PMID 31781561, 2019). "In a study, it showed that ZFAS1 was frequently elevated in hepatocellular carcinoma, which is in line with our results." (PMID 31775815, 2019).
hepatocellular carcinoma (continued). "In hepatocellular carcinoma, ZFAS1 expression was found increased in cancer tissues compared to normal tissues, and correlated with higher recurrence rates and shorter OS." (PMID 29163829, 2017). "In hepatocellular carcinoma, ZFAS1 functions as an oncogene in HCC progression by binding miR-150, which adsorbs ZEB1, MMP14 and MMP16 expression, and abrogating the tumor-suppressive." (PMID 29262629, 2017). "MiR-150-5p was revealed to target ZEB1 in various cancers such colon cancer, esophageal squamous cancer and ovarian cancer, and ZFAS1 was demonstrated to sequestrate miR-150-5p and exerted its pro-metastatic activity in hepatocellular cancer." (PMID 28697764, 2017). "ZFAS1 was reported to promote hepatocellular carcinoma metastasis via sponging miR-150 to activate ZEB1, MMP14, and MMP16." (PMID 28983240, 2017). "TRIBAL suppression strongly upregulated a low-abundance ZFAS1 variant in hepatocytes but not in hepatoma models." (PMID 41649053, 2026). "However, it was shown that lncRNA ZFAS1 targeting miR-150-5p exerts age-dependent expression in hepatocellular carcinoma, with higher expression in older compared to younger patients." (PMID 40868120, 2025). "This study presents a novel mechanism of ZFAS1 in the tumorigenesis of hepatocellular carcinoma." (PMID 36855431, 2023). "Furthermore, ZFAS1 has also been verified to interact directly with miR-150-5p to influence hepatocellular carcinoma cell proliferation, migration and invasion in vitro." (PMID 36855431, 2023). "However, more potential regulatory mechanisms of ZFAS1 in hepatocellular carcinoma still need to be analyzed, and the study of ZFAS1/miR-150-5p in hepatocellular carcinoma has not been reported." (PMID 36855431, 2023). "ZFAS1 promoted hepatocellular carcinoma cell proliferation, migration and invasion in vitro." (PMID 36855431, 2023). "The high expression of ZFAS1 may affect tumorigenesis in the progression of hepatocellular carcinoma." (PMID 36855431, 2023). "We used the hepatocellular carcinoma data obtained by TCGA to evaluate the prognostic value of ZFAS1 and analyzed the relationship between ZFAS1 and various tumor characteristics, highlighting the role of upregulation of ZFAS1 as an independent prognostic factor of poor OS." (PMID 36855431, 2023). "ZFAS1 was originally discovered to play a vital role in hepatocellular carcinoma progression; there ZFAS1 may be a potential tumor suppressor." (PMID 36240130, 2022). "In hepatocellular carcinoma, ZFAS1 can have both a tumor suppressive and oncogenic function." (PMID 33771981, 2021). "However, suppressor roles for ZFAS1 lncRNA in breast cancer and hepatocellular carcinoma have also been reported." (PMID 31010087, 2019). "In breast cancer its overexpression decreases apoptosis and enhances growth; in contrast, in hepatocellular carcinoma, the overexpression of the ZFAS1 gene and consequent binding of ZFAS1 protein to miR-150, prevents it from exerting its contrasting tumor suppressive effects." (PMID 29657260, 2016). "For instance, induction of lncRNA highly up-regulated in liver cancer (HULC), TCF7, and Zinc finger antisense 1 (ZFAS1) could promote tumorigenesis and metastasis of hepatocellular carcinoma (HCC)." (PMID 27589728, 2016). "ZFAS1 functions as a pivotal molecular hub in hepatocellular carcinoma (HCC), primarily through its role as a competitive endogenous RNA (ceRNA) to sponge tumor-suppressive microRNAs (miRNAs)." (PMID 41450817, 2026). "However, little is known about the functional significance of ZFAS1/miR-150-5p in hepatocellular carcinoma, and the potential molecular mechanism of miR-150-5p remains largely unknown in hepatocellular carcinoma." (PMID 36855431, 2023). "Therefore, the ZFAS1 gene may be a positive regulator of human hepatoma cell migration, with tumor promotion effects." (PMID 31781169, 2019).
hepatocellular carcinoma (continued). "After analyzing 11 lncRNA expression profiles of seven cancer types, we identified one validated translated lncRNA, ZFAS1, which was significantly up-regulated in hepatocellular carcinoma (HCC)." (PMID 31781169, 2019). "Importantly, ZFAS1 is known to promote metastasis in hepatocellular carcinoma." (PMID 28333948, 2017). "Concordantly with our results, in hepatocellular carcinoma (HCC) ZFAS1 was identified as one of the most frequently amplified genes based on the publicly available microarray data." (PMID 26506418, 2016). "The univariate Cox analysis results were consistent with the results of Kaplan-Meier curve analysis, which further indicated that ZFAS1, FBXL19-AS1 and AC068473.5 were prognostic factors in patients with hepatocellular carcinoma (p < 0.05)." (PMID 36855431, 2023). "To further verify ZFAS1 and FBXL19-AS1, we used qRT-PCR to analyze the differential expression of lncRNAs in 15 hepatocellular carcinoma tissues and 15 precancerous tissues." (PMID 36855431, 2023). "The results showed that the increased expression of ZFAS1 was significantly correlated with age, TNM stage and clinical stage of hepatocellular carcinoma patients (p < 0.05)." (PMID 36855431, 2023). "For instance, lncRNA ZFAS1 activated the expression of ZEB1, MMP-14 and MMP-16 to promote tumor growth and metastasis by sponging miR-150 in hepatocellular carcinoma." (PMID 31827393, 2019). "However, to date, the functional role and mechanism of ZFAS1 in ferroptosis in hepatocellular carcinoma (HCC) remains largely unknown." (PMID 39296014, 2024). "All the results showed that ZFAS1 and FBXL19-AS1 have significant prognostic significance in patients with hepatocellular carcinoma and could be used as independent prognostic factors for hepatocellular carcinoma." (PMID 36855431, 2023). "However, the data of ZFAS1 targeting miR-150-5p regulating hepatocellular carcinoma have not been reported yet, which may be a new mechanism of ZFAS1 regulating hepatocellular carcinoma." (PMID 36855431, 2023).
breast carcinoma (48 papers, 2013 to 2026). "In addition, ZFAS1 overexpression can significantly inhibit cell proliferation by causing cell cycle arrest and inducing apoptosis in breast cancer cells." (PMID 36530425, 2022). "ZFAS1 is down-regulated in breast cancer, and increasing ZFAS1 level may cause cell cycle arrest and apoptosis." (PMID 31191327, 2019). "Annotated lncRNAs already implicated in breast cancer (DSCAM-AS1, NEAT1, SNHG3, ZFAS1) also had a significant (FDR ≤ 0.3) effect, indicating the screen was able to identify functional lncRNAs." (PMID 38745269, 2024). "Accumulating studies have shown that lncRNAs such as MALAT1 and ZFAS1 are closely related to breast cancer." (PMID 36530425, 2022). "ZFAS1 was significantly downregulated in breast cancer tissue so that it can be considered a tumor suppressor." (PMID 35198599, 2021). "ZFAS1 (ZNFX1 antisense RNA 1), a lncRNA newly identified in 2011, is shown to be dysregulated in breast cancer." (PMID 34072570, 2021). "A recent review described that the majority of studies report that ZFAS1 has an oncogenic role, but ZFAS1 has a tumor suppressor role in breast cancer, and conflicting mechanisms have been reported in hepatocellular cancer." (PMID 33771981, 2021). "ZFAS1 has been shown to have a tumor suppressive function in breast cancer by decreasing cellular proliferation and migration." (PMID 33771981, 2021). "Deletion of lncRNA-Zfas1 in breast cancer cells resulted in increased cell proliferation with a concomitant reduction of Zfas1 expression." (PMID 34123857, 2021). "ZFAS1 has been reported to have an oncogenic role in various types of cancer, for example, bladder cancer, breast cancer, HCC, and CRC." (PMID 34571795, 2021). "ZFAS1, firstly studied in breast cancer by Marjan, is transcribed from the gene ZNFX1 on the antisense DNA strand near the 5′ end." (PMID 30288832, 2019). "ZFAS1 is up-regulated in cancers, excluding breast cancer, and regulates cellular phenotypes, EMT process, proliferation, migration, and invasion, and also affects apoptosis." (PMID 31010087, 2019). "Previously, ZFAS1 was shown to be downregulated in human breast cancer cells and ZFAS1 overexpression led to reduced cell migration and invasion through inhibition of EMT." (PMID 31881983, 2019). "Specifically, the expression of ZFAS1 was found to be upregulated in most cancers, except breast cancer." (PMID 30288832, 2019). "In breast cancer, ZFAS1 overexpression obviously inhibited cell growth by inducing cell cycle arrest and apoptosis, and suppressed cell migration and invasion by repressing EMT process." (PMID 29678899, 2018). "siRNA-mediated depletion of ZFAS1 in mammary epithelial cells increased cellular proliferation and promoted differentiation, indicating a crucial role of ZFAS1 in mammary development and breast cancer progression." (PMID 28099946, 2017). "ZFAS1, located at chromosomal band 20q13.13, was first reported dysregulated in breast cancer, suggesting a role of ZFAS1 in this type of cancer." (PMID 29137442, 2017). "ZFAS1 was found downregulated in breast carcinoma, which suggests ZFAS1 also as a possible tumour suppressor." (PMID 29138748, 2017). "Our earlier publication (2011), using a limited number of samples, suggested that ZFAS1 expression was down-regulated in breast cancer cells relative to normal breast epithelial cells." (PMID 27871336, 2016). "Discrepancy between TCGA and previous studies in regard to ZFAS1 expression in normal breast cells versus breast cancer cells should also be addressed in greater detail." (PMID 27871336, 2016). "Using human breast cancer cell lines, ZFAS1 was found to be expressed in all cell lines tested, albeit at different levels of abundance." (PMID 27871336, 2016). "The authors have focused on breast cancer cell lines, due to previous data linking ZFAS1 to mammary gland tissue development, and a previous report of decreased ZFAS1 in invasive ductal breast carcinoma in humans." (PMID 27871336, 2016).
breast carcinoma (continued). "They revealed contrasting observations to our results (decreased levels of ZFAS1 in tumor tissue, increase in cell proliferation after ZFAS1 silencing), and considered ZFAS1 as tumor suppressor gene in breast cancer." (PMID 26506418, 2016). "Here we extended the previous study and investigated functions of ZFAS1 in breast cancer cell lines." (PMID 27871336, 2016). "To further investigate the possible role of ZFAS1 in ribosome function, we treated breast cancer cells with the translation elongation inhibitors puromycin and cycloheximide." (PMID 27871336, 2016). "Authors’ response: Our earlier publication (2011), using a limited number of samples, presented preliminary evidence that ZFAS1 expression was down-regulated in breast cancer cells relative to normal breast epithelial cells." (PMID 27871336, 2016). "We have added “Our earlier publication (2011), using a limited number of samples, suggested that ZFAS1 expression was down-regulated in breast cancer cells relative to normal breast epithelial cells." (PMID 27871336, 2016). "The expression of these ribosomal protein genes was also correlated with that of ZFAS1 in breast cancer samples, showing moderate positive correlations (r = 0.41–0.60)." (PMID 27871336, 2016). "In mouse mammary gland we have see similar pattern of expression for and the ribosomal proteins and Zfas1 which are consistance with some of breast cancer data derived from TCGA." (PMID 27871336, 2016). "Further, they propose a mechanism in which ZFAS1 is required for the production of 45S rRNA as well as for RPS6 phosphorylation in breast cancer cells." (PMID 27871336, 2016). "And how do they motivate their interest in elucidating ZFAS1 biology in the context of normal breast vs breast cancer cells?" (PMID 27871336, 2016). "To further analyse ZFAS1 expression and to characterise its function, we have used breast cancer as our model system." (PMID 27871336, 2016). "ZFAS1 is located in the 20q13.13 region, which functions in breast cancer progression." (PMID 36240130, 2022). "LncRNA ZNFX1 antisense RNA 1 (ZFAS1) levels were downregulated in breast cancer tissues, and silencing ZFAS1 expression obviously promoted the cell proliferation of MDA-MB-231 by activating the signal transducer and activator of the transcription 3 (STAT3) pathway." (PMID 36613528, 2022). "The expression of ZFAS1 is low in breast cancer cells, and it has antitumor activity." (PMID 34771549, 2021). "ZFAS1 was first reported as a tumour suppressor gene in breast cancer." (PMID 34552050, 2021). "For example, lncRNA LINC00899 suppresses breast cancer progression by inhibiting miR-425, lncRNA ZFAS1 regulates oesophageal squamous cell carcinoma cell malignant behaviours via the miR-124/STAT3 axis and lncRNA MALAT1 promotes GBM proliferation and progression by targeting the miR-199a/ZHX1 axis." (PMID 33832517, 2021). "ZFAS1 was first identified as a tumour suppressor gene in breast cancer." (PMID 34552050, 2021). "For example, ZFAS1 was first introduced as a tumor suppressor in breast cancer." (PMID 32760219, 2020). "It was found for the first time that ZFAS1 served as a tumor suppressor in breast cancer." (PMID 33202381, 2020). "In breast cancer cells overexpressing Zfas1, the EMT-related markers, such as E-cadherin expression, were upregulated while N-cadherin and vimentin expressions were downregulated, indicating that the effects of Zfas1on cell migration and invasion were partially associated with the EMT process." (PMID 31231466, 2019). "ZFAS1, located at chromosomal band 20q13.13, was reported as an important player to regulate the development of human cancers including glioma, lung, ovary, gastric, and breast cancer." (PMID 31736958, 2019). "Furthermore, in breast cancer Zfas1 inhibited cell proliferation, migration, invasion, and the EMT process." (PMID 31231466, 2019). "The expression and function of ZFAS1 in breast cancer is different from that in other cancers." (PMID 30186041, 2018).